EGFR (epidermal growth factor receptor)
Diseases named in the same sentence as EGFR in open-access papers (continued):
Sharing a sentence is not in itself a finding about the gene and the disease.
oral squamous cell carcinoma (continued). "Epidermal growth factor receptor (EGFR) is well known as a general prognostic biomarker for head and neck tumors, however the specific prognostic value of EGFR in oral squamous cell carcinoma (OSCC) is controversial." (PMID 35957892, 2022). "Overexpression of EGFR has an unfavorable clinical outcome, poor prognosis, and low survival rates in Oral Squamous Cell Carcinoma (OSCC)." (PMID 36010285, 2022). "Tissue microarrays with specimens of a large cohort of oral squamous cell carcinoma (n=222) were immunohistochemically stained to determine the expression of PD-L1, EGFR, and COX-2 and the amount of infiltrating NK cells and CD8-positive T cells." (PMID 34395287, 2021). "Epidermal growth factor receptor (EGFR) is highly expressed in several types of cancer cells including oral squamous cell carcinoma (OSCC)." (PMID 32901097, 2021). "The IL-1β is another inflammatory and cancer-related cytokine which has been recently found to affect EGFR transactivation in oral squamous cell carcinomas." (PMID 33924087, 2021). "Higher epidermal growth factor receptor (EGFR) signaling can contribute to tumor metastasis and resistance to therapies in oral squamous cell carcinoma (OSCC)." (PMID 33889303, 2021). "Epidermal growth factor receptor (EGFR) is highly expressed in several carcinomas including oral squamous cell carcinomas (OSCC)." (PMID 32901097, 2021). "The amplification of the well-known oncogenes CCND1 and EGFR was associated with a metastatic lymph node, as shown by the OS and DFS in a previous oral squamous cell carcinoma (OSCC) study in Taiwan." (PMID 34070941, 2021). "In fact, contrary to our observations, the knockdown of Fucosyltransferase 1 in OC2 cells of oral squamous cell carcinoma, which decreases EGFR fucosylation, correlates with an increase in EGFR degradation." (PMID 33238647, 2020). "The clinical efficacy of anti-epidermal growth factor receptor (EGFR) antibody cetuximab for oral squamous cell carcinomas (OSCCs) is low." (PMID 33019722, 2020). "Overexpression and increased signalling from the epidermal growth factor receptor (EGFR)often change oral squamous cell carcinoma (OSCC) and thus EGFR is frequently targetedmolecularly by the therapeutic antibody cetuximab." (PMID 31496355, 2019). "Epidermal growth factor receptor (EGFR) and activin A are both overexpressed in oral cavity squamous cell carcinoma (OSCC)." (PMID 30914776, 2019). "This study investigates differences in the effects on cell growth of cetuximab and EGFR TKI AG1478 at the molecular level using oral squamous cell carcinoma (OSCC) cell lines." (PMID 31615015, 2019). "It has been reported that TFF3 acts through EGFR to activate downstream pathways including p44/42MAPK, while the inhibition of p44/42MAPK specifically abrogated migratory properties of oral squamous-cell carcinoma cells stimulated by exogenous TFF341,42." (PMID 31685806, 2019). "We also showed that metastatic oral squamous cell carcinoma cells markedly secrete EVs enriched with stemness marker molecule EpCAM, oncogenic EGFR, and stress resistant proteins HSP90s, whose targeting reduced survival of the metastatic cells." (PMID 30364132, 2018). "The EGFR and downstream signaling pathways play an important role in tumorigenesis in oral squamous cell carcinoma (OSCC)." (PMID 28854970, 2017). "Identified potential biomarkers of metastatic oral squamous cell carcinoma includes E-cadherin, integrins, matrix metalloproteinases (MMPs), IL-8, chemokine receptor 7 and EGFR." (PMID 28592923, 2017). "We investigated the therapeutic effect of EGFR-MBs in oral squamous cell carcinoma by administration of BLM and EGFR-MBs coupled with US." (PMID 28938010, 2017). "We labeled endogenous EGFR with GFP by genome-editing of human oral squamous cell carcinoma cells, which were used to examine EGFR-GFP behavior in mouse tumor xenografts in vivo." (PMID 29268862, 2017).
oral squamous cell carcinoma (continued). "We have demonstrated that sonoporation with EGFR-MBs is an effective targeted drug delivery system for oral squamous cell carcinoma." (PMID 28938010, 2017). "This study demonstrated that the use of EGFR-MBs combined with US exposure enhanced BLM delivery in an oral squamous cell carcinoma model." (PMID 28938010, 2017). "When the EGFR kinase activity is targeted by therapeutic drugs, the oral squamous cell carcinoma cells lose proliferative ability, making these reagents effective in targeting oral squamous cell carcinoma cells." (PMID 26919318, 2016). "The aim of this study was to investigate the selective killing effect of cold atmospheric pressure plasma with dysfunction of the EGFR in oral squamous cell carcinoma." (PMID 26919318, 2016). "Nitric oxide scavenger pretreatment in cell culture media before CAP treatment rescued above degradation and dysfunction of the EGFR as well as the killing effect in oral squamous cell carcinoma." (PMID 26919318, 2016). "It is known that Cetuximab inhibits oral squamous cell carcinoma invasion and metastasis directly via degradation of epidermal growth factor receptor and indirectly via inhibition of neo-angiogenesis." (PMID 26575422, 2016). "Degradation and dysfunction of EGFR were only observed in EGFR-overexpressing oral squamous cell carcinoma cells." (PMID 26919318, 2016). "A previous report demonstrated that the combination of cetuximab and celecoxib significantly reduced EGFR phosphorylation, which contributed to the inhibition of tumor growth in human oral squamous cell carcinoma." (PMID 26491668, 2015). "The EGFR nuclear localization was also observed in oral squamous cell carcinoma and in the epithelium of inflammatory fibrous hyperplasia." (PMID 25991665, 2015). "Most of the studies reported were documented on the correlation of EGFR with oral squamous cell carcinoma while there are quite a few studies elaborating the association between oral potentially malignant lesions and the upregulation of EGFR receptor." (PMID 26697149, 2015). "In conclusion, the results of this study suggested that EGFR over-expression can be one of the useful diagnostic markers for predicting the potential biologic behavior of OL and OSMF transforming into oral squamous cell carcinoma." (PMID 26697149, 2015). "The effectiveness of near-infrared imaging (NIR) interrogation of epidermal growth factor receptor (EGFR) expression as a sensitive biomarker of oral squamous cell carcinoma (OSCC) response to arsenic trioxide therapy was studied in mice." (PMID 23029451, 2012). "In contrast, in oral squamous cell carcinoma (OSCC), a significant reduction in the percentage of ciliated cells was found in oral leukoplakia (OLK), especially in patients with OSCC, and EGFR was a target, suggesting that loss of cilia induced oral tumor growth." (PMID 38499532, 2024). "KRT17 is known to be a direct target of miR-485, while the signaling cascade involving miR-485/KRT17 may result in suppressing EGFR in oral squamous cell carcinoma cell lines." (PMID 36902387, 2023). "Moreover, 6-shogaol induces apoptosis by inhibiting the EMT phenomenon and the EGFR/PI3K/Akt pathway in oral squamous cell carcinoma." (PMID 36768961, 2023). "While the development and progression of oral squamous cell carcinoma (OSCC) are known to be driven via EGFR-HB-EGF and EGFR-EREG interactions in OSCC cells, pain is associated with EREG- or HB-EGF-mediated activation of EGFR." (PMID 38004424, 2023). "Furthermore, CAP reportedly has selective anti-tumor effects against oral squamous cell carcinoma by triggering nitric oxide (NO)-induced dysfunction of epidermal growth factor receptor (EGFR)." (PMID 37241912, 2023). "The aim of this systematic review and meta-analysis was to evaluate the current evidence in relation to the clinicopathological and prognostic significance of epidermal growth factor receptor (EGFR) overexpression in patients with oral squamous cell carcinoma (OSCC)." (PMID 37569265, 2023).
oral squamous cell carcinoma (continued). "The majority of oral squamous cell carcinoma (OSCC) cancers overexpress the epidermal growth factor receptor (EGFR/ErbB1/HER1), and links have been made between higher expression levels and an aggressive phenotype, a poor prognosis, and resistance to anticancer therapy." (PMID 36381928, 2022). "The use of EGFR inhibitors on oral squamous cell carcinoma (OSCC) as monotherapy yielded modest clinical outcomes and therefore would benefit from biomarkers that could predict which patient subsets are likely to respond." (PMID 30787334, 2019). "We recently showed that anti-EGFR therapeutic antibody cetuximab is secreted with EVs by oral squamous cell carcinoma cells, suggesting that cancer cells could secrete redundant and toxic substances using this process." (PMID 30364132, 2018). "Our study demonstrated that EGFR-targeted sonoporation with MBs may hold promise as new effective therapies for oral squamous cell carcinoma." (PMID 28938010, 2017). "CAP may be a promising cancer treatment method by inducing EGFR dysfunction in EGFR-overexpressing oral squamous cell carcinoma via nitric oxide radicals." (PMID 26919318, 2016). "This combination-based therapy with CAP may potentiate EGFR-inhibitor targeted therapy in oral squamous cell carcinoma cells." (PMID 26919318, 2016). "In summary, treatment with CAP may be a promising cancer treatment by targeting EGFR dysfunction in EGFR-overexpressing oral squamous cell carcinoma cells via generation of NO radicals in the applied solution." (PMID 26919318, 2016). "The aim of this study is to investigate the effects of cold atmospheric pressure plasma (CAP)-induced radicals on the epidermal growth factor receptor (EGFR), which is overexpressed by oral squamous cell carcinoma, to determine the underlying mechanism of selective killing." (PMID 26919318, 2016). "The application of anti-EGFR therapies, including monoclonal antibodies target at the receptor’s surface or tyrosine kinase inhibitors targeting its intracellular domain, has shown encouraging results in canine tumors and oral squamous cell carcinoma in cats, particularly with Cetuximab." (PMID 38248333, 2024). "In addition, genistein and curcumin have also been identified as RTK inhibitors, which cause EGFR tyrosine phosphorylation and inhibition of EGFR downstream signaling molecules Akt, ERK1/2, and STAT3 in oral squamous cell carcinoma, thus exhibiting potent cancer chemopreventive activity." (PMID 36430361, 2022). "In oral squamous cell carcinoma, IGFBP3 induces radiotherapy resistance through interaction with DNA-PKcs and EGFR." (PMID 41199784, 2025). "Resveratrol administration also increases the sensitivity of oral squamous cell carcinoma to cetuximab by decreasing the protein expression of uPAR, which inhibits the signaling molecule ERK1/2 downstream of EGFR." (PMID 40490812, 2025). "Further studies on oral squamous cell carcinoma cells have revealed that IL-1β mediates the formation of the chemokine CXCL1, which leads to a transactivation of EGFR via the G protein-coupled receptor CXCR2." (PMID 34205482, 2021). "The link between EGFR signalling, EMT and EV secretion is readily apparent in Oral Squamous Cell Carcinoma (OSCC) cell line HSC-3, where exposure to EGF induces both EMT and an enrichment of EGFR in the EVs secreted by the cancer cells." (PMID 33302515, 2020). "Oral squamous cell carcinoma (OSCC)-derived exosomes carrying EGFR transformed normal epithelial cells into a mesenchymal phenotype, and the anti-EGFR therapeutic antibody cetuximab inhibited this carcinogenic effect of TEX." (PMID 32517240, 2020). "EGFR (AG1478 and cetuximab) and MET (SU11274) inhibitors also induced changes in actin cytoskeleton organization of oral squamous cell carcinoma cells." (PMID 31649529, 2019).
oral squamous cell carcinoma (continued). "In oral squamous cell carcinoma (OSCC), although GALNT2 expression can also modify the O-glycosylation of EGFR, it can facilitate the activation and downstream signaling of EGFR, thereby enhancing OSCC cell migration and invasion." (PMID 27686492, 2016). "Application of scavengers of NO to the cultures before CAP treatment rescued degradation and dysfunction of EGFR, as well as the killing effect of subsequent CAP treatment in oral squamous cell carcinoma cells." (PMID 26919318, 2016). "Hyperactivation of the epidermal growth factor receptor (EGFR) pathways and chronic inflammation are common characteristics of oral squamous cell carcinoma (OSCC)." (PMID 26462152, 2015). "Another EGFR inhibitor, PD153035, inhibits phosphorylation of EGFR and STAT3 in vivo and prevents oral squamous cell carcinoma growth and proliferation." (PMID 24743778, 2014). "In oral squamous cell carcinoma, SGLT1/EGFR expression was inversely related to tumor differentiation." (PMID 25254045, 2014). "The combination of EGFR, HER-2/neu and HER-3 expression is a stronger predictor for the outcome of oral squamous cell carcinoma than any individual isoform." (PMID 23563900, 2013). "The epidermal growth factor receptor (EGFR) is a member of a family of tyrosine kinase receptors that are overexpressed in several types of cancers, including the oral squamous cell carcinoma (OSCC)." (PMID 22322523, 2012). "A definitive therapy for oral squamous cell carcinoma (OSCC) in dogs remains elusive; directing efforts toward targeting EGFR and COX-2 in veterinary clinical oncology holds promise in unveiling fresh perspectives on cancer biology and the efficacy of advanced targeted therapies." (PMID 38248333, 2024). "In oral squamous cell carcinoma, high BST2 expression could induce gefitinib resistance by regulating the EGFR pathway." (PMID 36594082, 2023). "Epidermal growth factor receptor (EGFR) plays an important role in the progression of oral squamous cell carcinoma(OSCC), but the relationship between metformin and EGFR expression in OSCC remains unclear." (PMID 35222283, 2022). "Alternatively, as CCND1 amplifications are also most frequently seen in HPV-independent VSCC, it might be worth exploring the potential additive oncogenic effects of EGFR and CCND1 alterations, as recently shown in oral squamous cell carcinomas." (PMID 34209172, 2021). "EGFR homodimers or heterodimers in combination with other HER members, such as HER2 and HER3, activate downstream signaling cascades in many types of cancer, including oral squamous cell carcinoma (OSCC)." (PMID 32218834, 2020). "Thus, this study was done to identify predictors of response to CTh with docetaxel-based regimen in locally advanced oral squamous cell carcinoma and correlated the tumor response with HPV status, EGFR, Her-2-neu, and GADD45 expression." (PMID 29386013, 2018). "Degradation and dysfunction of EGFRs were observed only in the EGFR-overexpressing oral squamous cell carcinoma and not in the normal cell." (PMID 26919318, 2016). "Despite the known crosstalk between ADAM17 and EGFR, which has been considered a promising targeted therapy in oral squamous cell carcinoma (OSCC), the role of ADAM17 in OSCC development is not clear." (PMID 24495306, 2014). "Similarly both growth factors were detected in oral squamous cell carcinomas and a highly significant inverse correlation was found between the levels of TGF-alpha and the epidermal growth factor receptor in these tumours." (PMID 2478181, 1989). "Epidermal growth factor receptor (EGFR) plays a pivotal role in oral mucosal cells in regulating cell cycle, proliferation, differentiation and transformation, and it is commonly overexpressed in oral squamous cell carcinoma cells compared to normal oral mucosal cells." (PMID 26919318, 2016).
oral squamous cell carcinoma (continued). "In human malignant oral squamous cell carcinoma (OSCC) cells, the fucosylation of N-glycan antennae is lacking in EGFR, while indolent cells have high levels of fucosylation at the N420 and N579 sites of EGFR." (PMID 33531990, 2021). "Using routine biopsy tissue, the application of FISH technique for EGFR amplification and CDKN2A deletion distinguished oral squamous cell carcinoma from non-cancerous dysplasia with high specificity, improved diagnostic performance, and identified patients with poorer survival." (PMID 41463200, 2025). "Aim of the study was to study the effect of neoadjuvant chemotherapy with docetaxel and carboplatin in locally advanced non-metaplastic oral squamous cell carcinomas and to correlate the tumor response and survival with HPV status, EGFR, Her-2-neu, and GADD45 expression." (PMID 29386013, 2018).